CD4 (CD4 molecule)
Diseases named in the same sentence as CD4 in open-access papers (continued):
Sharing a sentence is not in itself a finding about the gene and the disease.
AIDS (continued). "Immunoactivation facilitates HIV-1 replication and leads to CD4+ T cell depletion and AIDS pathogenesis, but it is unclear whether Nef expression in HIV-1 infected DCs plays a role in activating CD4+ T cells and enhancing cell-to-cell transmission." (PMID 22479639, 2012). "Despite lower CD4 cell count at cART initiation, after TB is excluded as an AIDS-defining event, estimated time to clinical AIDS for individuals from SSA cohorts is similar to that of Europeans." (PMID 22412867, 2012). "Twenty-six persons (54%) were not at an advanced stage of HIV disease (no prior AIDS events, and CD4 cell counts >200/mm3), and the median CD4 cell count was 241/mm3 (interquartile range: 52–423/mm3)." (PMID 23056308, 2012). "Without CD4+ T cells, AIDS patients become hypersusceptible to pathogens that normally inhabit in tissues without much harming, and die of the opportunistic infections." (PMID 25408871, 2012). "It discriminated patients at different HIV/AIDS stages, duration of ART, and CD4 cell count." (PMID 23116130, 2012). "Other characteristics associated with more available creatinine measurements included lower baseline CD4, higher nadir CD4, prior AIDS diagnosis, older age, and non-white race." (PMID 22911697, 2012). "Among the 25 persons who were diagnosed late (with AIDS or a CD4 cell count ≤350/mm3), 15 (60%) had not been tested before, compared to 29% (6/21) of those not presenting late (p = 0.042)." (PMID 23056308, 2012). "The demonstration that SAMHD1 restricts HIV-1 replication in quiescent CD4+ T-cells could have an important implication in our understanding of HIV-1-mediated CD4+ T-cell depletion and establishment of the viral reservoir, two of the HIV/AIDS hallmarks." (PMID 23092122, 2012). "Similarly, CD4 independent HIV-1 has been recovered from the CNS of HIV + individuals and (very rarely) AIDS patients with extreme CD4+ cell depletion, in some cases from CD8+ cells." (PMID 22830620, 2012). "The existence of a set-point in CD4+ T-cell count is not a problem per se because if its value is sufficiently low, it can be argued to correspond to the AIDS phase." (PMID 23202449, 2012). "Lower CD4 cell count, not being on HAART, higher VL, and partial and complete anergic DTH response all remained associated with an increased risk of AIDS or death." (PMID 22457767, 2012). "In the early days of the HIV epidemic, it was observed that a minority of the infected patients did not progress to AIDS or death and maintained stable CD4+ cell counts." (PMID 22693657, 2012). "In conclusion, although Africans in SSA and Europe demonstrated a slower rate of CD4 cell decline and higher rates of tuberculosis than non-African Europeans, survival rates and AIDS rates, excluding TB, were similar." (PMID 22412867, 2012). "It is noteworthy that 60% of persons diagnosed late in the infection (with AIDS or a CD4 cell count <350/mm3) had never been tested before, highlighting the fact that expanded HIV screening would be helpful for patients who have been infected for a long time." (PMID 23056308, 2012). "Finally, when we included data from the 469 individuals with only one CD4 cell count while ART-naïve and AIDS-free, our main findings remained practically unchanged." (PMID 22412867, 2012). "CD4 decline, severe thrombocytopenia, increased plasma viral loads and occurrence of opportunistic infections were also observed in the HIV-1 experimentally infected chimpanzees that developed AIDS in the Yerkes Primate Center." (PMID 21232091, 2011). "The utility of the WHO-defined stage 1 and 2 clinical factors used in WHO HIV/AIDS clinical staging in predicting low CD4 cell count has not been established in Uganda." (PMID 21589912, 2011). "According to the National AIDS control program (NACP) guidelines, ART is initiated for HIV-infected individuals with CD4+ T lymphocyte counts below 350 cells per microliter of blood, and 500 cells per microliter threshold is commonly used to increase patient monitoring intensity." (PMID 21754988, 2011).
AIDS (continued). "In a cohort with free access to healthcare, independent of established predictors of AIDS and CD4 recovery during HAART, cumulative VL and virologic decay patterns were associated with AIDS and distinct aspects of CD4 reconstitution." (PMID 21625477, 2011). "The primary outcome is a composite of time from baseline to reduction of CD4 T lymphocyte count below 350 cells/mm3 (confirmed by two measures at least one week apart), or start of ART, or the emergence of a documented CDC-defined AIDS-defining illness." (PMID 21838913, 2011). "The WHO HIV/AIDS clinical staging guidelines have a low sensitivity and about half of the participants in stages 1 and 2 would be eligible for ART initiation if they had been tested for CD4 count." (PMID 21589912, 2011). "CD4+ T cells, the main targets for HIV infection, are rapidly depleted during HIV infection, eventually leading to the acquired immunodeficiency syndrome known as AIDS." (PMID 21943070, 2011). "Factors associated with achieving CD4 T-cell counts >200cells/μl included higher baseline CD4 T-cell count (p<0.001), not having a prior AIDS-defining illness (p = 0.018) and higher baseline HIV RNA (p<0.001)." (PMID 21674057, 2011). "Mean values of CD4/CD8 ratio for EC were 0.18 which was lower than 0.40 in another study that also concluded that when CD4/CD8 ratio is less than 0.5 in patients with EC, it appears to be of prognostic significance as 80% of patients developed AIDS at a median of 3 months." (PMID 22046186, 2011). "Despite the wide use of the WHO HIV/AIDS clinical guidelines in Ugandan primary health care facilities, they have not yet been evaluated in Uganda against the new CD4 cut-offs for ART eligibility of <250cells/mm3 and <350 cells/mm3." (PMID 21589912, 2011). "At the time of the acute HCV infection diagnosis, 44 men (55.0%) were HIV diagnosed before 2000, 8 men (10.0%) had a previous diagnosis of AIDS-defining illness, 14 (17.5%) had CD4 cell counts below 350/mm3 and 24 (30.0%) had no antiretroviral treatment." (PMID 22216248, 2011). "We found that none of these measures predicted change in CD4 count at any time point after initiation of ART, especially after adjustment for other known predictors of CD4 response such as pre-ART CD4 count, HIV viral load, or history of WHO Stage 4 AIDS defining illness." (PMID 22216334, 2011). "Comparison between two late entry criteria—inclusion and non-inclusion of asymptomatic individuals with CD4+ T cell counts ≤350/mm3—in terms of their impact on AIDS mortality rates, 2003–2006." (PMID 21283618, 2011). "Plasma HIV-1 RNA levels have been shown to be a strong predictor of rapid progression to AIDS after seroconversion that is independent of CD4+ counts." (PMID 22046186, 2011). "However, these associations are weaker than those observed between CD4 count, viral load, AIDS-free survival, and the size of the DEM CD4 T cell population." (PMID 21526194, 2011). "We examine the impact of changing the eligibility criterion for antiretroviral therapy from CD4 count <200 to CD4 count <350 on the number of person-years on ART, the number of AIDS deaths averted, and the costs of the change including the costs of additional tests and recruitment costs." (PMID 21490782, 2011). "In multivariate analysis adjusting for baseline CD4+ and post-HAART time interval, CD4+ responses were poorer in those with: longer time from HIV SC to HAART start, lower pre-HAART CD4+ nadir, higher pre-HAART VL, and clinical AIDS before HAART (P < 0.05)." (PMID 21244701, 2011). "As a group, they had left ventricular hypertrophy, and a large proportion of participants had AIDS (median nadir CD4: 120) where no man in the current study had AIDS." (PMID 22151886, 2011). "With regards to CD4 T cell counts the apoptosis of lymphocytes by free radicals leads to progression of immunodeficiency and makes for a quicker transition from HIV infection to AIDS." (PMID 22164280, 2011).
AIDS (continued). "Even though 46.9% of the total study population were defined as being at only WHO Stage 1 for AIDS, they were already on HAART, indicating that their CD4 count rates were below 200 cells/mm3 and this was confirmed by the median baseline CD4 count of 81 cells/mm3 (IQR: 29-149)." (PMID 21923929, 2011). "The proportion of patients who were LP was 55.6% (1,393 persons) and 38.5% had advanced HIV infection (15.2% presenting with CD4 < 200 cell//μl and 23.3% with AIDS regardless of the CD4 cell count)." (PMID 21729332, 2011). "Rwanda's national ART guidelines recommend initiating antiretroviral treatment for all individuals with CD4<350 cells/μl (regardless of AIDS symptoms), as well as for those in the most advanced clinical disease stage (regardless of CD4 count)." (PMID 21949704, 2011). "In Western countries therapy for HIV-1 infection is recommended when the CD4 count falls below 350×106/L, still above the cut-off of 200×106/L that strongly predicts AIDS, while evidence from non-randomized studies support treatment initiation below 500×106/L." (PMID 21494630, 2011). "The low CD4+ T cell counts observed in AVL co-infected patients cannot be solely explained by lymphocyte depletion related to HIV-1 replication, since low CD4+ T cell counts were observed in AVL/HIV-AIDS patients with undetectable or low viral load levels." (PMID 21171992, 2010). "We carried out survival analyses of patients from the 23 cohorts of the CASCADE (Concerted Action on SeroConversion to AIDS and Death in Europe) collaboration with a known date of HIV seroconversion and with at least two CD4 measurements prior to initiating cART." (PMID 20186270, 2010). "Expansion of non-CD4-expressing cells of the innate immune system with IFNγ-producing capacity, in particular NK cells and γδ-T cells, could compensate for lost IFNγ production by CD4+-T cells, particularly in advanced HIV/AIDS." (PMID 21048923, 2010). "The importance of CD4+ T cell preservation in this disease is highlighted by findings in African green monkeys infected with SIVagm: despite high viral replication, their CD4+ T cell counts remain normal, and they do not develop AIDS." (PMID 20617170, 2010). "Concurrent with this finding was that improved HIV status, as measured by the lack of AIDS diagnosis, lower HIV RNA levels, and high CD4 counts, was associated with increased weight gain similar to other studies." (PMID 20419086, 2010). "Finally, our study results reveal that eligible patients (CD4 < 200 cells/μL and/or WHO stage IV AIDS) are gradually enrolling at a slightly earlier stage of HIV infection." (PMID 20594326, 2010). "In this connection, these ATL/HIV-AIDS patients in remission phase apparently recovered their lymphocyte levels (data not shown) since they have much higher CD4+ T cell counts than those previously observed in patients with active disease." (PMID 21171992, 2010). "In contrast, CD4+ T counts in ATL-HIV/AIDS patients were similar to HIV-1 infected patients without leishmaniasis." (PMID 21171992, 2010). "Linear gingival erythema (652±299) is not characteristic of AIDS and lack of a significant relation between this lesion and CD4 count was justified." (PMID 23346337, 2010). "We find that the CD4 slope is not predictive of future AIDS events or deaths if cART is initiated immediately, i.e., both patients are expected to have a similar outcome in this situation." (PMID 20186270, 2010). "HIV-1 viral load in AVL/HIV-AIDS was not correlated with CD4+ T cell count, since low or undetectable levels of HIV-1 were seen even in patients with very low CD4+ T cells counts." (PMID 21171992, 2010). "We used Cox proportional hazards models adjusted on CD4+ lymphocytes (CD4), gender, age, HIV transmission category, antiretroviral therapy, cotrimoxazole prophylaxis, statin treatment, viral load and previous AIDS diagnosis." (PMID 20126646, 2010).
AIDS (continued). "Conditions traditionally considered non-AIDS related, such as cardiovascular, renal, hepatic, and neurologic diseases, as well as certain types of cancers, are becoming the dominant comorbidities in patients on long term ART with CD4 >200cells/mm3." (PMID 20500898, 2010). "Median CD4 count at baseline was significantly lower in the AIDS patients at pre-treatment time point compared to the non-AIDS (p-values in each HIV-strata <0.001, analysis not shown)." (PMID 20843322, 2010). "Although loss of CD4+ T cells is responsible for the profound T-cell immunodeficiency of AIDS, APC dysfunction in HIV+ individuals could accelerate or exacerbate CD4+ T-cell dysfunction." (PMID 20209134, 2010). "In the case of the first patient (aged 30 years, no hepatitis coinfection and AIDS defining illness, and concurrent CD4 count 200 cells/μL), the CD4 count continues to increase with HIV VL up to 20 000 copies/mL during 6-12 months after cART initiation." (PMID 21182796, 2010). "Across all sites, 35% were female, median age was 37 years, median CD4 count was 105 cells/μL (interquartile range [IQR]: 38, 200), 47% of subjects had clinical AIDS, and 78% of subjects had either CD4<200 cells/μL or clinical AIDS." (PMID 20531956, 2010). "The participant recruitment in this study was undertaken regardless of the baseline CD4+ cell counts or presence of symptoms of cervical cancer or HIV/AIDS." (PMID 20072610, 2010). "We did not observe differences in CD4 cell count or time since AIDS diagnosis between septic and nonseptic groups." (PMID 20698966, 2010). "Low CD4 cell counts, time since AIDS diagnosis, HAART treatment, or AIDS stage of disease, conversely, were not identified as risk factors for mortality in the post-HAART era." (PMID 20698966, 2010). "Moreover, in another study done also in Uganda, patients who developed an AIDS-defining condition according to the WHO clinical staging system within 12 weeks pre or post ART initiation, took longer to achieve an increase in CD4 count of 50 cells/mm3." (PMID 20479873, 2010). "A previous study in Northern Italy showed that patients infected with HIV through injecting drug use, patients without AIDS diagnosis, or patients with higher CD4 counts are more likely to miss medical appointments and discontinue their follow-up." (PMID 20565935, 2010). "In an adjusted Cox model, the hazard ratio for AIDS or death was 1.01 (95% CI 0.97–1.04) for each 10 cells/μl per year reduction in pre-cART CD4 cell decline, and multivariate Cox models with and without pre-cART CD4 slope had identical c indices of 0.70." (PMID 20186270, 2010). "The mean viral load in plasma was high (230,767 HIV-1 RNA copies/ml) consistent with advanced HIV-1 disease, but, while the mean CD4+ T-cell count was low (255.6 cells/mm3), it never fell below AIDS levels in almost half of the patients." (PMID 20211031, 2010). "The CD4 values did not vary significantly across HIV-type in either the AIDS patients (pre-treatment time point) or non-AIDS groups (AIDS cohort, p-value = 0.55; non-AIDS cohort, p-value = 0.36; analysis not shown)." (PMID 20843322, 2010). "Information on CD4+ count was not available either, but a relationship between SCCC/dysplasia risk and presence of AIDS was observed." (PMID 19997105, 2010). "In the study of people with HIV-AIDS, recorded CD4 cell counts and undetectable viral loads in the medical notes confirmed the poorer health status of those with lower health literacy." (PMID 20687946, 2010). "Further we observed in our study population, presence of patients with CD4 T cell counts well above 200 cells/uL and with chronic HIV associated symptoms without any AIDS defining illness." (PMID 20626905, 2010). "We found that, despite clinical remission of leishmaniasis, AVL co-infected patients presented a more severe immunossupression as suggested by CD4+ T cell counts under 200 cells/mm3, differing from ATL/HIV-AIDS cases that tends to show higher lymphocytes levels (over 350 cells/mm3)." (PMID 21171992, 2010).
AIDS (continued). "The response to antiretroviral therapy was however comparable between monoinfected and coinfected patients in terms of CD4 cell count increase (p = 0.8), HIV-1 viral load below 400 copies/mL (p = 0.9), death (p = 0.3) and death or new AIDS-defining event (p = 0.1)." (PMID 20193053, 2010). "As expected, co-infected individuals presented a stable CD4+ T lymphocytosis irrespective of their progression to AIDS, contrasting with the depletion of CD4+ T cells counts observed among HIV patients over time." (PMID 20028500, 2009). "Twenty-five percent of IDUs were diagnosed with HIV and AIDS at the same time, and among those IDUs 38.2% had very low CD4+ T-cell counts at HIV diagnosis (<50 cells/μL) (data not shown)." (PMID 19214229, 2009). "Although having the same clinical spectrum, HIV-2 infection is characterized by a strikingly lower viremia and a much slower rate of CD4 decline and AIDS progression than HIV-1, irrespective of disease stage." (PMID 19936055, 2009). "On the other hand, international guidelines for HAART therapy in chronically HIV-1-infected adults recommend beginning these regimens in those individuals with an AIDS-defining illness, in HIV-1 positive pregnant women, and in patients with a CD4+ T-cell count lower than 350 cells/μL." (PMID 19538732, 2009). "None of the subjects developed AIDS-defining conditions or CD4+ counts ≤200 cells/ul during the study." (PMID 19479055, 2009). "Since CD4+ helper T cells play a central role in the maintenance of effective antibody and CTL responses to viral infections, these responses are likely to be an important component of an effective AIDS vaccine." (PMID 19165322, 2009). "Such progressive decline in CD4+ T cells is also observed in some but not all simian immunodeficiency virus (SIV) macaque models for AIDS." (PMID 19360097, 2009). "It does not downmodulate CD4 to a greater extent than pre-AIDS Nefs, nor does it more greatly enhance infectivity in a single round assay compared to the pre-AIDS Nefs from the same patient." (PMID 18510766, 2008). "These variables included follow-up CD4 cell count (Wald test P = 0.32), baseline CD4 cell count (Wald test P = 0.46), baseline WHO stage (Wald test P = 0.50), incident AIDS (Wald test P = 0.22), age (Wald test P = 0.09), gender (Wald test P = 0.63), and socio-economic status (Wald test P = 0.53)." (PMID 18601727, 2008). "The difference between mean CD4+ T cells among people living with HIV/AIDS (PLWHA) infected with tuberculosis and those PLWHA not infected with tuberculosis is not statistically significant (p = 0.2)." (PMID 18826574, 2008). "Sialoadhesin mRNA copy numbers did not correlate with CD4+ cell counts in AIDS patients (Pearson correlation coefficient = −0.125, p = 0.51)." (PMID 17330143, 2007). "Since 1993, when CD4 T-lymphocyte count <200 cells/μL became an AIDS-defining condition in the United States (although not in Europe), US AIDS surveillance programs have seen a decrease in the collection of information on OI diagnoses." (PMID 17850671, 2007). "Thus, specific CD4+ and CD8+ T cell functional responses to specific CMV antigens appear to be good candidates for identifying protective immunity against AIDS-related CMV disease." (PMID 17388670, 2007). "Low CD4 counts, AIDS, and no current use of highly active antiretroviral therapy (HAART) are strongly correlated with hospitalizations especially those due to opportunistic infections." (PMID 17343729, 2007). "Infection with human immunodeficiency virus type 1 (HIV-1) causes depletion of CD4+ T-cells, and without highly active antiretroviral therapy (HAART) results in acquired immunodeficiency syndrome (AIDS)." (PMID 19088897, 2007). "In the context of an HIV infected subject with latent pulmonary TB, progressing to AIDS stage of HIV disease, the acute stage of the infection is characterized by eventual depletion in the number of CD4+ T-cells, the key orchestrator of all immune mechanisms in the body." (PMID 18053126, 2007).